ALB (albumin)
Diseases named in the same sentence as ALB in open-access papers (continued):
Sharing a sentence is not in itself a finding about the gene and the disease.
nephrotic syndrome (continued). "Patients who reached the outcome had higher baseline creatinine and BUN, lower albumin, more frequent nephrotic syndrome and active smoking, and lower response rates to immunosuppression." (PMID 41501143, 2026). "His nephrotic syndrome relapsed in September 2023 with uPCR 800 mg/mmol and serum albumin 29 g/L with positive PLA2R titre 19 RU/mL." (PMID 39979558, 2025). "A 72-year-old woman presented in July 2022 with a 4-month history of nephrotic syndrome with preserved renal function, uPCR 458 mg/mmol, and serum albumin 21 g/L." (PMID 39979558, 2025). "The significant reduction in proteinuria (median reduction of 89.2% at week 52) and improvement in serum albumin levels indicate substantial resolution of nephrotic syndrome, a key determinant of long-term renal outcomes in LN." (PMID 40963616, 2025). "Tacrolimus was reintroduced, but the patient was lost to follow-up until December 2024, when he presented with severe nephrotic syndrome (serum albumin 9 g/L, UPCR 166 mg/mmol, serum creatinine 61 μmol/L)." (PMID 41409283, 2025). "Median (IQR) proteinuria was 9.2 (6.7–11.9) g/24 h, and median (IQR) serum albumin was 2.7 (2.2–3.2) g/dl, with nephrotic syndrome present in 136 patients (85.5%)." (PMID 40814621, 2025). "Several previous systematic reviews have attempted to assess the role of intravenous albumin in oedematous or hypoalbuminaemic patients, but all have critical limitations that restrict their applicability to children with nephrotic syndrome." (PMID 41281089, 2025). "Current evidence for intravenous albumin in hospitalised children with nephrotic syndrome is very limited." (PMID 41281089, 2025). "Clinical presentation varies, with some cases resembling primary FSGS with full nephrotic syndrome, while others present with proteinuria and normal serum albumin, similar to secondary FSGS." (PMID 40115110, 2025). "Nephrotic syndrome (NS) typically involves proteinuria, reduced levels of albumin in the blood, and swelling." (PMID 40357065, 2025). "Nephrotic syndrome pathophysiology is anchored in glomerular injury that manifests in excess proteinuria, low levels of albumin in blood, and swollen tissues." (PMID 40909076, 2025). "This Danish multicenter, cross-sectional study included 47 adult patients with nephrotic syndrome, defined by plasma-albumin <30 g/L and urine albumin-creatinine ratio >2200 mg/g." (PMID 40478760, 2025). "The co-administration of furosemide and albumin in patients with nephrotic syndrome is debated in the literature." (PMID 40698215, 2025). "Three months ago, her urine protein was elevated and her serum albumin concentration was decreased, resulting in the pathophysiology of nephrotic syndrome secondary to DKD." (PMID 40276452, 2025). "Adequately powered, blinded RCTs should be conducted in children with nephrotic syndrome to evaluate the efficacy and safety of albumin + diuretic therapy." (PMID 41281089, 2025). "Renal disease, particularly nephrotic syndrome, can induce hypothyroidism through urinary losses of thyroid-binding globulin, albumin, and iodine, leading to reduced T3/T4 levels and impaired hormone synthesis." (PMID 41217125, 2025). "With treatment, clinical indicators of nephrotic syndrome improved since serum albumin increased from 19.8 to 29.1 g/L and urine protein declined from 1.76 to 1.17 g/L over the initial three cycles." (PMID 40603713, 2025). "The markedly low serum albumin level, combined with an extremely high urine albumin concentration, confirms nephrotic-range proteinuria and supports the diagnosis of nephrotic syndrome." (PMID 41426863, 2025). "At diagnosis, 91.1% had nephrotic syndrome, with proteinuria of 10.2 ± 9.8 g/day, serum albumin of 23.7 ± 6.5 g/L, and estimated glomerular filtration (eGFR) of 66.7 ± 27.7 mL/min/1.73m2." (PMID 41307422, 2025).
nephrotic syndrome (continued). "Together, these reviews highlight a critical gap in the evidence base: the near-complete absence of high-quality randomised trials evaluating intravenous albumin in children with nephrotic syndrome." (PMID 41281089, 2025). "We searched PubMed, Cochrane CENTRAL, Google Scholar and Europe PMC from January 1, 1990, to June 30, 2025, using MeSH terms and free-text keywords for nephrotic syndrome, albumin and paediatric populations." (PMID 41281089, 2025). "The severity of this membrane dysfunction correlates with the clinical severity of nephrotic syndrome, as reflected in laboratory findings such as increased proteinuria and decreased serum albumin concentrations." (PMID 40603713, 2025). "Serum albumin levels decreased from 40.0 (38.0–42.0) g/l to 29.5 (26.0–35.0) g/l (P-value < 0.001), and 5 of 16 patients had authentic nephrotic syndromes." (PMID 40225389, 2025). "Lastly, it is necessary to develop consensus guidelines based on available evidence to guide albumin use in paediatric nephrotic syndrome." (PMID 41281089, 2025). "We concluded that evidence supporting IV albumin use in hospitalised children with nephrotic syndrome is extremely limited." (PMID 41281089, 2025). "Their ultimate conclusion, that there was insufficient evidence to recommend routine albumin use in nephrotic syndrome, remains in alignment with our findings, although their inclusion of a non-English language study diverges from our eligibility criteria." (PMID 41281089, 2025). "Further workup confirmed nephrotic syndrome with 24-hour urinary protein at 5.6g/day and serum albumin of 26 g/L." (PMID 39792734, 2025). "Factors that promote ALB metabolism (such as hyperthyroidism, nephrotic syndrome, and glucocorticoid usage) can diminish ALB glycosylation levels." (PMID 39958689, 2025). "The included study was an open-label, randomised crossover trial conducted in India, comparing IV albumin plus furosemide to furosemide alone in children with nephrotic syndrome and persistent oedema." (PMID 41281089, 2025). "One week after discharge from the hospital on 4 January 2023, despite optimal symptomatic treatment, the patient’s nephrotic syndrome worsened (serum albumin concentration of 8 g/L and ACR of 10 g/g), and his creatinine level increased to 200 μmol/L." (PMID 38540991, 2024). "One month later, his nephrotic syndrome achieved complete remission with urine protein of 0.3g/day and albumin of 35.4g/L." (PMID 38765016, 2024). "Nephrotic syndrome is a significant worldwide health concern impacting millions of people and is marked by heavy proteinuria, edema, and decreased serum levels of albumin." (PMID 38993428, 2024). "Other than a low nutritional status, albumin levels can also be decreased by other conditions such as nephrotic syndrome, impaired liver function, and inflammatory diseases." (PMID 38791890, 2024). "At the onset of nephrotic proteinuria following the transplantation, individuals with nephrotic syndrome exhibited lower serum albumin levels, although they were still above the lower limit of normal." (PMID 38672122, 2024). "Possible explanations for the wide range of outcomes are the etiology of nephrotic syndrome, age, differences in hypervolemic status, serum albumin and serum creatinine levels, salt intake, and different treatment approaches." (PMID 38540182, 2024). "Patients in the FSGS+ group represented more severe nephrotic syndrome with a higher 24-h proteinuria of a median level of 5.61 g/24 h and a lower serum albumin of a median level of 20.4 g/L than the FSGS- group." (PMID 38716932, 2024). "We observed a significantly lower level of proteinuria, a lower proportion of nephrotic syndrome (p < 0.05) and a higher level of serum albumin (p < 0.05) in the ANCA-positive group than in the ANCA-negative group." (PMID 39388045, 2024).
nephrotic syndrome (continued). "Irrespective of factors such as gender, age, BMI, blood pressure, albumin level, the presence of massive proteinuria or severe nephrotic syndrome, effectively controlling the TG/HDL-C ratio demonstrated a significant decrease in the risk of TA." (PMID 38327562, 2024). "We found that the weight and ALB decreased in the nephrotic syndrome rats induced by doxorubicin, while 24-hour urine protein, BUN, Scr, TC, and TG increased." (PMID 38995910, 2024). "And all of them presented with nephrotic syndrome, with a high level of urinary protein (7.2 ± 3.0 g/24 h) and a low level of serum albumin (19.4 ± 2.7 g/L)." (PMID 39027416, 2024). "The authors recommended evaluating children with nephrotic syndrome for the presence of infection when they had low serum levels of albumin and hematuria and were from rural areas." (PMID 38987746, 2024). "Four months after the last dose of rituximab (March 2021), he developed nephrotic syndrome with proteinuria increasing to 5.45g/day and serum albumin of 27 g/L, although his serum creatinine remained stable." (PMID 38765016, 2024). "In this report, we used stringent inclusion criteria requiring the presence of both nephrotic syndrome (≥ 3.5 g of proteinuria, ≤ 3.5 g/dL serum albumin) and ≥ 80% of foot process effacement to assemble a relatively pure cohort of DP/primary FSGS." (PMID 36911713, 2023). "The Spearman’s rho correlation coefficients of urinary NGAL with age, albumin, cholesterol, urinary creatinine, urinary protein, and urine protein/creatinine ratio in nephrotic syndrome patients were calculated." (PMID 36874337, 2023). "The positive association between albumin and PON-1 has been described in dogs and humans in various diseases such as parvovirus enteritis and nephrotic syndrome." (PMID 36669034, 2023). "Serum albumin levels were higher, and the combined nephrotic syndrome clinical score was lower in C3 siRNA-treated mice than control siRNA-treated mice." (PMID 36709213, 2023). "Previous work had shown that nephrotic syndrome in mice and albumin exposure to podocytes in vitro increase TNF-RNA61, which in turn can induce podocyte injury and glomerular disease progression." (PMID 36922538, 2023). "Patients with primary FSGS have nephrotic syndrome with serum albumin below 3.5 gm/dl besides nephrotic range proteinuria." (PMID 37203968, 2023). "In general, diagnostic value of commonly used indicators for thrombosis in patients with nephrotic syndrome is limited due to the presence of low albumin, elevated D-dimer, and decreased AT-III levels resulting from pathological characteristics." (PMID 37753194, 2023). "All three IMN patients presented with nephrotic syndrome, with proteinuria ranging from 4.35 to 15.25 g per 24 h and serum albumin ranging from 14.5 to 28.8g/L." (PMID 37731504, 2023). "Huangqi, an important herb in Touxie-Jiedu-Zhiyang decoction and UCG, has been shown to be beneficial in alleviating nephrotic syndrome by increasing plasma albumin and reducing excretion of urine albumin." (PMID 36297351, 2022). "5.Treat pregnant women with severe nephrotic syndrome and serum albumin <25 g/l with LMWH in prophylactic or, if necessary, therapeutic doses based on any additional thrombosis risk factors." (PMID 36506226, 2022). "And we found that serum IL-35 levels were positively correlated with ALB (r=0.37, P<0.01) and remission (r=0.28, P=0.01), and negatively correlated with 24hUTP (r=-0.26, P=0.02), nephrotic syndrome state (r=-0.39, P<0.01) and remission time (r=-0.46, P<0.01)." (PMID 35983038, 2022). "Another key finding was that, in patients with nephrotic syndrome, serum albumin was found to be a tool for assessing the extent of proteinuria." (PMID 35295594, 2022). "Compared to MN, patients with cIgAN/MN had a lower proportion of nephrotic syndrome and a lower level of albumin-to-creatinine ratio." (PMID 35359934, 2022).
nephrotic syndrome (continued). "Patients with MN and nephrotic syndrome, especially those with albumin levels of 2.2 g/dl, are more likely to have thromboembolic events." (PMID 36439574, 2022). "The albumin serum level can also decrease following protein-energy wasting with nephrotic syndrome and it is frequently used as a nutritional status marker." (PMID 34334135, 2021). "Due to a nephrotic syndrome with high levels of proteinuria (190 mg/dl, normal range: 0–25) and hypoproteinemia (4 g/dl, normal range: 5.7–8.2), she started treatment with albumin infusions." (PMID 34202629, 2021). "After admission to the hospital due to oedema of both the lower extremities, the patient was diagnosed with nephrotic syndrome due to abnormal 24-h urine protein (7540 mg) and blood albumin (25 g/L) levels." (PMID 34376183, 2021). "In nephrotic syndrome, the albumin concentration drops to 7–25 g/L (normal concentration in adults; 42.0 ± 3.5 g/L)." (PMID 34638659, 2021). "Our study shows that nephrotic syndrome is the main clinical manifestation of the two groups, but from the level of serum ALB and 24 h-TP, HBV-MN and IMN can’t be distinguished in patients with HBV infection." (PMID 34526634, 2021). "One of the most important clinical manifestations of nephrotic syndrome is increased urinary protein and decreased albumin level." (PMID 34508140, 2021). "There was evidence of nephrotic syndrome with a serum albumin level of 1.8 g/dL, urine protein level of 3+ (773 mg/dL), urine albumin/creatinine ratio of 4296 mg/g Cr, and hyperlipidemia." (PMID 34664831, 2021). "In the one rituximab-treated patient with nephrotic syndrome, the serum albumin normalised in parallel with neurological improvement." (PMID 34400540, 2021). "Serum albumin and urinary protein are generally used to quantitatively evaluate the severity of nephrotic syndrome in MN, which are important indicators for assessing disease activity." (PMID 35111055, 2021). "The majority of patients had nephrotic syndrome (81.5%), the median level of 24-h proteinuria and the mean serum albumin were 8.7 g/d (IQR: 5.2–15.4) and 2.79 ± 0.65 g/dL, respectively." (PMID 34203607, 2021). "At the age of 15 years, she developed recurrent nephrotic syndrome (serum creatinine 87 μmol/L, serum albumin 21 g/L, UPCR 6.4 g/10 mmol)." (PMID 32447506, 2020). "A 2-year-old female child had nephrotic syndrome (urine protein-creatinine ratio 749.1 mg/mg; blood urea nitrogen 11 mg/dL; serum creatinine 0.3 mg/dL; and serum albumin 1.8 g/dL)." (PMID 33203378, 2020). "Nephrotic syndrome that presents with a very low serum albumin represents a prothrombotic condition with a high incidence of venous thromboembolism." (PMID 33175249, 2020). "Laboratory tests showed mild renal dysfunction (serum creatinine level of 1.27 mg/dL) and full nephrotic syndrome (serum albumin 1.3 g/dL and proteinuria 6.4 g/day)." (PMID 32640739, 2020). "As a result of this treatment under good adherence and tolerance, proteinuria gradually decreased and serum albumin increased up to 3.5 g/dL, resulting in nephrotic syndrome remission 2 months after clarithromycin administration." (PMID 32569182, 2020). "Oral clarithromycin for asymptomatic sinusitis gradually improved proteinemia in parallel with the increases in serum albumin and complement levels, resulting in nephrotic syndrome remission." (PMID 32569182, 2020). "She had obvious edema occult blood 3+, urinary protein 3.2 g/24 h, albumin 17.6 g/L, and total cholesterol 7.21 mmol/L, consistent with a diagnosis of nephrotic syndrome." (PMID 33203428, 2020). "According to the Japanese clinical practice guideline for nephrotic syndrome, nephrotic syndrome in children is defined as the presence of massive proteinuria (≥40 mg/h/m2) plus hypoalbuminemia (serum albumin ≤2.5 g/dL)." (PMID 32838745, 2020).
nephrotic syndrome (continued). "At last follow-up 16 months after initiation of IS therapy, renal function recovered (serum a creatinine 0.85 mg/dL) and the nephrotic syndrome was in partial remission (proteinuria 2.6 g/day and serum albumin 3.3 g/dL)." (PMID 32640739, 2020). "This Caucasian female patient presented in 2004, at the age of 6 years, with nephrotic syndrome (urine protein level 19.8 g/L, serum albumin 21 g/L)." (PMID 32447506, 2020). "The initial evaluation showed increased serum creatinine (4.29 mg/dL) and nephrotic syndrome (proteinuria 13.4 g/day and serum albumin 2.8 g/dL)." (PMID 32640739, 2020). "Patients affected by nephrotic syndrome have an increase in albumin synthesis and in the fractional catabolic rate, with consequent rapid albumin turnover." (PMID 33187372, 2020). "Forty-two (61.8%) PMN patients had a nephrotic syndrome with a mean serum albumin of 23.15 ± 7.67 g/l and a median 24-hour proteinuria of 4.17 [2.42–6] g." (PMID 33002091, 2020). "Similar to patients with nephrotic syndrome, decreased serum levels of albumin, immunoglobulins, and antithrombin III have been frequently observed in patients with IBD, as well as increased levels of factor V, factor VII, and factor VIII." (PMID 30651128, 2019). "One patient had nephrotic syndrome and received albumin and diuretics; 3 patients had reduced GFR and proteinuria." (PMID 30800660, 2019). "Patients with nephrotic syndrome therefore not only lose massive amounts of albumin but also large amounts of DBP (having a lower molecular weight than albumin)." (PMID 31998239, 2019). "Elevated plasma levels of alpha-2-macroglobulin, along with Fibrinogen and albumin levels, is commonly seen in nephrotic syndrome." (PMID 31159152, 2019). "Partial remission of nephrotic syndrome was achieved at six-month postoperatively, with urinary protein excretion 2.0 g/24 h, serum albumin 35.0 g/L, normal serum creatinine (80.0 μmol/L) and eGFR (90.4 ml/min/1.73m2)." (PMID 31771524, 2019). "All patients had typical features of MCNS at diagnosis, with nephrotic syndrome in all cases (mean proteinuria of 7.96 g/day (range: 3.33 to 14.8 g/day) and a mean albumin concentration of 17.5 g/L (7.7 to 29.5 g/L)." (PMID 30458703, 2018). "Her initial serum albumin level was 12 g/L, and a 24-hour urine protein output was quantified at 8.14 g/day; she was diagnosed as having nephrotic syndrome." (PMID 29740522, 2018). "This was the first pharmacoeconomic study in Brazil examining the use of human albumin among patients with nephrotic syndrome." (PMID 28443947, 2017). "Patients with nephrotic syndromes have urinary losses of proteins that bind thyroid hormones, including thyroxine binding globulin, transthyretin, and albumin." (PMID 28117377, 2017). "Nephrotic syndrome with the albumin serum level over 2gr/dl was the most common situation for which albumin was improperly applied." (PMID 28979337, 2017). "The cost-effectiveness results, and especially the cost-utility results of this study provided information on the use of human albumin among patients with nephrotic syndrome." (PMID 28443947, 2017). "One of the formal indications for the use of human albumin stated within the scope of ANVISA’s guidelines is nephrotic syndrome (NS)." (PMID 28443947, 2017). "Twenty-two cases had proteinuria and serum albumin, of which 15 met the definition of nephrotic syndrome (proteinuria >3.5 g/24 h and serum albumin <3.0 g/dl)." (PMID 28877681, 2017). "The aim of this study was to analyze albumin use among patients with nephrotic syndrome, from the perspective of the Brazilian National Health System (Sistema Único de Saúde, SUS), through a pharmacoeconomic study." (PMID 28443947, 2017). "The majority of renal diseases leading to hypogammaglobulinemia are nephrotic syndrome, where IgG is lost accompanied by albumin." (PMID 27531123, 2017).